ALB (albumin)
Diseases named in the same sentence as ALB in open-access papers (continued):
Sharing a sentence is not in itself a finding about the gene and the disease.
liver disease (continued). "In addition, subjects with high FIB-4 index showed low white blood cell counts and albumin levels, which might have been related to splenomegaly and portal hypertension due to advanced liver fibrosis." (PMID 36411436, 2022). "Clearly defined categories such as “albumin”, “ascites”, “Child–Pugh” and partly “hepatitis”, “jaundice”, and “liver cirrhosis” are often not used to represent a contraindication, but rather to define or clarify less certain terms, such as liver disease/impairment/insufficiency." (PMID 35407541, 2022). "A change in albumin level or PT may be associated with a decrease in liver functioning mass, although neither is specific for liver disease." (PMID 36275793, 2022). "The serum albumin redox state has long been viewed as a biomarker of systemic oxidative stress, as the redox state shifts to a more oxidized state in response to the severity of the pathological condition in various diseases such as liver diseases and renal failures." (PMID 33804859, 2021). "Our study showed that multiple logistic regression for the serum 25-OHD and serum albumin levels in association with HE revealed positive OR, confirming our theory that the low serum level of 25-OHD is associated with increased severity of the liver disease and HE." (PMID 33628512, 2021). "In our study, preoperative low serum ALB was significantly associated with short-term and long-term prognosis in cardiac surgery patients without liver disease and could serve as an independent risk factor for mortality." (PMID 34790710, 2021). "Finally, LEE occurred more frequently in patients with pre-existing liver disease or with other markers of liver injury, such as low albumin or higher GGT, supporting the hypothesis of a liver origin of transaminase release instead of a muscular one." (PMID 33339330, 2020). "Therefore, we speculate that ALB::GFP iHep cells can provide a suitable model to study drug development in vitro or treat human hepatic diseases in vivo." (PMID 32746905, 2020). "Although this result is concordant with previous studies that related QT interval prolongation with the severity of liver disease, yet lower serum albumin level in prolonged QTc group is unlikely to be the cause of QTc prolongation as the albumin levels in both groups are still within normal values." (PMID 31659581, 2019). "Therefore, these factors limit the use of albumin as an early indicator of hepatic disorders." (PMID 30581572, 2018). "However, increased levels of sCD163 were associated to disease severity and low albumin levels, but not to portal hypertension." (PMID 30183743, 2018). "In this case, peak conjugated bilirubin might be a surrogate marker of severity of liver disease; a similar explanation might be used for lowest albumin concentrations—which are also markers of chronic disease- and were also independently associated with CA duration." (PMID 28792509, 2017). "In addition, previous studies have demonstrated that the ligand binding property of site II was impaired under oxidative stress conditions and the reduced binding capacity of the albumin site II is mainly related to the impaired liver function in advanced liver disease." (PMID 27873095, 2017). "Patients with vitamin B12 values >1000 pg/mL were characterized by significantly reduced concentrations of albumin, prealbumin and cholinesterase, which are all indices of synthetic hepatic function; this evidence is consistent with vitamin B12 metabolism and previous reports in liver diseases." (PMID 28025528, 2016). "Moreover, as shown in the present study, we also found an association between RDW and the severity of the liver disease, and patients with higher values of RDW tended to be older, had lower levels of hemoglobin, total protein, and serum albumin, and had higher INR and total bilirubin." (PMID 22649548, 2012). "In advanced liver disease, the serum albumin level may be less than 3.5 g/dl." (PMID 21194423, 2010).
liver disease (continued). "Clinical Applications: In hepatorenal syndrome (HRS), albumin combined with vasoconstrictors like terlipressin improves renal function and survival." (PMID 41827398, 2026). "At this time, more attention should be paid to the low serum-ascites albumin gradient (SAAG)‍, which is the core indicator for excluding portal hypertension." (PMID 41404586, 2025). "In this case, contrast-enhanced CT demonstrated classic findings, which were supported by paracentesis showing a high serum-ascites albumin gradient (SAAG), consistent with portal hypertension." (PMID 41416273, 2025). "Diagnostic paracentesis yielded clear yellow fluid with a serum-ascites albumin gradient (SAAG) of 1.54 g/dL, consistent with portal hypertension." (PMID 41416273, 2025). "The ascitic fluid analysis showed a high serum-ascites albumin gradient (SAAG) of 2.4, consistent with portal hypertension secondary to BCS." (PMID 40292150, 2025). "The albumin–bilirubin (ALBI) grade is an emerging tool for liver function assessment, predicting the prognosis of patients with liver diseases through serum albumin and bilirubin levels." (PMID 40692980, 2025). "This may be explained by the fact that serum albumin is influenced by multiple factors other than inflammation, including nutritional intake, fluid status, protein losses during dialysis, comorbid conditions such as liver disease, and the presence of protein-energy wasting." (PMID 40596989, 2025). "The Albumin–Bilirubin (ALBI) index reflects hepatic functional reserve based on serum albumin and bilirubin levels, while the Platelet–Albumin–Bilirubin (PALBI) index adds platelet count to account for portal hypertension and inflammation-related factors." (PMID 40508934, 2025). "Beyond established covariates (Daily dose, ALB, eGFR, PLT, urea), we newly identified five clinical variables (HGB, AST, IBIL, TBIL, and DBIL) as mechanistic predictors of TEIC exposure in liver disease patients." (PMID 41424785, 2025). "The Child-Pugh prognostic scoring criteria used in liver failure include clinical findings, such as encephalopathy, ascites, and liver disease, as well as numerical laboratory parameters, such as INR, albumin, and total bilirubin." (PMID 38496192, 2024). "The serum albumin-ascites gradient (SAAG) from his initial paracentesis was 1.4, indicating the etiology was from portal hypertension." (PMID 38586670, 2024). "Albumin is often used for plasma volume expansion, but its efficacy in cirrhotic patients with AKI [excluding hepatorenal syndrome (HRS)] is debated." (PMID 39434907, 2024). "AST, ALT, albumin, and TBIL are important indices of liver function and are closely related to liver diseases, such as hepatic fibrosis." (PMID 39771147, 2024). "The levels of albumin, INR or PT reflect the synthetic function of the liver, and these are also the prognostic indicators for liver disease." (PMID 38818349, 2024). "Other biomarkers were also altered further indicating liver disease and metabolic disturbance such as alkaline phosphatase (ALP), albumin, triglycerides, lactate, and total proteins." (PMID 39652585, 2024). "Terlipressin improved renal function and reversed Hepatorenal syndrome in a higher proportion of patients with Hepatorenal syndrome type 1 and Systemic Inflammatory Response Syndrome (SIRS) than patients who received albumin plus placebo." (PMID 39286706, 2024). "Albumin infusion can regulate fluid balance, effectively treat ascites, prevent paracentesis-induced circulatory dysfunction (PICD), and aid in managing hepatorenal syndrome (HRS) and spontaneous bacterial peritonitis (SBP)." (PMID 38551716, 2024). "In patients with sonographic signs of liver disease, PPV increased to 84.1% (95%CI: 73.3-94.9%) when platelet count and albumin were low but dropped to 20.8% (95%CI: 15.4-26.3%) when both were normal." (PMID 39559436, 2024). "Compared by the etiology of the liver disease, the NBNC group showed a significant decrease in albumin (p = 0.021)." (PMID 38355630, 2024).
liver disease (continued). "Based on the five variables of ascites, hepatic encephalopathy, albumin, prothrombin time, and total bilirubin, the CTP classification is a valuable tool for assessing liver disease severity." (PMID 37998586, 2023). "Model for end-stage liver disease score (MELD), albumin‒bilirubin (ALBI) score and Child‒Pugh score have been associated with postoperative complications." (PMID 37892021, 2023). "Those properties make albumin solutions essential in the treatment of spontaneous bacterial peritonitis (SBP), hepatorenal syndrome, and refractory ascites." (PMID 36676081, 2023). "Patients who developed AKI in this study had laboratory values suggesting more advanced liver disease: higher bilirubin and INR and lower albumin and sodium values." (PMID 35237687, 2022). "LFI only had a weak correlation with measures of liver function and portal hypertension such as MELD, albumin or platelets." (PMID 35626226, 2022). "The ALBI score, a score to assess liver dysfunction calculated based on albumin and total bilirubin, was increased in CVID patients after diagnosis of portal hypertension." (PMID 35821451, 2022). "Patients after diagnosis of portal hypertension displayed significant increases in alanine transaminase (ALT), gamma-glutamyltransferase (γ-GT), and ALP, while serum albumin and total protein were decreased." (PMID 35821451, 2022). "HCC patients were found to have lower serum levels of total cholesterol, albumin and platelet and higher levels of gammaGT and AST but these findings probably reflect a higher proportion of patients with advanced liver disease." (PMID 35745223, 2022). "Because local anaesthetic binds to plasma proteins—primarily α1-acid glycoprotein and albumin—changes in plasma protein concentrations may also influence the pharmacokinetics of a local anaesthetic and are affected by surgical trauma and systemic disease (cardiac, renal, and liver disease)." (PMID 35893804, 2022). "The BR bilirubin-binding capacity of each adsorbent was evaluated both in bovine serum albumin (BSA) solution and in plasma obtained from a patient with liver disease." (PMID 34986721, 2022). "Paracentesis revealed an elevated serum-ascites albumin gradient (SAAG), concerning portal hypertension." (PMID 36321002, 2022). "This is because, in patients with liver diseases including NAFLD, the synthesis of albumin by the liver is altered which leads to lower albumin concentration." (PMID 35174195, 2021). "Terlipressin is now recognized as effective in controlling acute kidney injury by hepatorenal syndrome (HRS-AKI), especially with the concomitant use of albumin infusion, as prescribed in the EASL clinical practice guidelines." (PMID 34070416, 2021). "The predictive power on mortality of low albumin levels in an unselected acutely admitted medical population (5894 adult patients) found an OR of 3.91 when adjusting for CRP, liver disease, renal disease, cancer and rheumatologic disease." (PMID 33956870, 2021). "Previous studies found that globulin increased, albumin decreased, and albumin/globulin decreased in METH-abuser serum, indicating that METH would induce hepatic disease and inflammation." (PMID 34381368, 2021). "Patients who developed HE in this study had laboratory values suggesting more advanced liver disease: highly elevated bilirubin and INR and lower albumin, platelet, and sodium values." (PMID 33425806, 2020). "The biochemical data related to nutritional status, including total cholesterol, serum albumin, transferrin, prealbumin, and CRP, are influenced by medical conditions, including malignancy, liver disease, infection, stress, and critical illness." (PMID 32053672, 2020). "Albumin and bilirubin comprise 2 of 3 objective components of the CPS, an established measure of severity of liver disease." (PMID 33425806, 2020). "Other indicators of liver disease occurring in CCHFV infected animals included a significant decrease in total protein and albumin (ALB) levels." (PMID 31557262, 2019).
liver disease (continued). "On the contrary, albumin, the most abundant protein in the plasma, decreases in most hepatic diseases, notably in ALD where ethanol inhibits albumin synthesis." (PMID 31531108, 2019). "MSC therapy improved the MELD score, ALB, ALT, and TBiL levels, and PT of patients with liver disease." (PMID 29562935, 2018). "The Child-Pugh classification system takes into consideration the synthetic function of the liver (albumin, INR, and bilirubin) and the clinical presentations of the portal hypertension (ascites and hepatic encephalopathy)." (PMID 30515332, 2018). "L/Smean ratio was strongly correlated to individual quantitative components (albumin, bilirubin, INR) and portal hypertension but was less correlated to the ALBI grade." (PMID 27349530, 2016). "The following baseline characteristics were significant predictors of liver disease diagnosis: increasing GGT, decreasing albumin, alcohol dependency, being female, increasing ALP, living in a deprived area and younger age." (PMID 24889852, 2014). "While we successfully isolated cells from all types of liver disease, we showed that ALD livers produced the poorest results and that cells isolated from ALD livers had inferior metabolic function in terms of albumin and urea synthesis." (PMID 24642019, 2014). "The initial diagnosis of liver diseases is carried out by routine liver function tests like serum level of ALT, AST, ALP, bilirubin, albumin, globulin, and so forth." (PMID 24696531, 2014). "Multivariate analysis according to the Cox regression model included treatment modality, age, sex, etiology of liver disease, pre-existing HE, Child's class, bilirubin, ALT, albumin levels, and ascites." (PMID 23606833, 2013). "The serum and fluid albumin values were 33 g/L and 25 g/L, respectively, giving a serum-ascites albumin gradient (SAAG) of 8 g/L, suggestive of non-portal hypertension ascites." (PMID 21696639, 2011). "Additionally, in specific Homo sapiens populations, such as patients with liver disease, careful consideration is required when interpreting NPAR due to potential confounding factors affecting neutrophil and albumin levels." (PMID 41036272, 2025). "The NIS database does not include specific laboratory values, including albumin, kidney function, or Model for End-Stage Liver Disease score, to assess the severity of liver disease." (PMID 41049900, 2025). "IL-32 did not correlate with albumin levels and the correlation with bilirubin, AST, ALT, and GGT does not necessarily indicate an association of IL-32 with liver disease." (PMID 40149726, 2025). "The principal features include APACHE, length of hospital stay before ICU admission, length of ICU stay, AST, SBP, albumin, Charlson, history of malignant cancer, platelet, age, OASIS, FiO2, history of liver disease, BUN, GCS, total bilirubin, admission weight, DBP, and base excess." (PMID 40351465, 2025). "In the present study, serum RBP levels had the strongest correlation with serum albumin levels, suggesting that RBP levels may accurately reflect the severity of liver disease." (PMID 39927287, 2025). "The addition of albumin, creatinine, the presence of liver disease, sex, height and age to parameters did not provide any significant improvement in the model fit." (PMID 40558149, 2025). "Age, gender, ascites, hepatic encephalopathy, bacterial infections, gastrointestinal bleeding, hepatorenal syndrome, TBIL, ALB, INR, PTA, WBC, NLR, CR, Na, MELD score, MELD-Na score, and ALBI score were identified as factors significantly associated with patient mortality (p < 0.05)." (PMID 39835109, 2024). "This novel scoring system evaluates liver function based solely on serum albumin and bilirubin levels, demonstrating prognostic value across various liver diseases, irrespective of etiology." (PMID 39766066, 2024).
liver disease (continued). "In this multi-center retrospective study, we developed a simple score composed of six variables (age, ascites, albumin, PT, TBIL, and sodium) to predict the 1-year and 3-year survival of TIPS treatment for patients with viral hepatitis cirrhosis-related portal hypertension." (PMID 39403285, 2024). "Compared with those in the derivation cohort, the patients in the derivation cohort had lower serum albumin levels, lower platelet count, higher LSM, and higher FIB-4 scores, indicating that worse liver function, more severe fibrosis and greater portal hypertension." (PMID 38664813, 2024). "Absence of portal hypertension, higher albumin and baseline platelet levels were found to be protective against carcinogenesis." (PMID 36983196, 2023). "ECOG PS was not correlated with serum albumin (P = 0.489), transpeptidase levels (P = 0.839), portal hypertension (P = 0.897), BCLC stage (P = 0.897) or Child–Pugh classification (P = 0.109)." (PMID 36726082, 2023). "The levels of sodium, potassium, albumin, creatinine, and lipids were within the normal range, indicating the absence of kidney, heart, and liver disorders." (PMID 37629098, 2023). "Usually, in liver diseases, synthesis of this protein decreases, but in this study after administration of ethanol, it is noted that the values of total protein, globulin, and albumin neither increased nor decreased, the values just are in the normal range." (PMID 36466417, 2022). "Notably, in liver disease and cirrhotic patients, the total concentrations and free fractions of vitamin D metabolites correlate to the DBP and albumin concentrations compared to controls." (PMID 35182287, 2022). "In both total PPH and PPH without liver disease groups, a greater incidence of hospital mortality was reported during the 1st quartile for ALB, whereas a greater proportion of hospital mortality was observed within the 4th quartile for AST." (PMID 35722097, 2022). "Preoperative low albumin has been identified as an independent risk factor for postoperative morbidity and mortality after CRS irrespective of a pre-existing liver disease even in highly advanced surgery within enhanced recovery pathways." (PMID 35814748, 2022). "Thus, ALB:GLO ratio is an index used to track changes in serum or plasma composition and predict liver disorders, and its normal value lies between 1.1 and 2.5 in case of humans." (PMID 35514333, 2022). "Of note, many of the other laboratory parameters indicated a reduced synthesis capacity of the liver, such as lower albumin and Quick when compared to patients without manifest portal hypertension, although values were often still within the normal range." (PMID 35821451, 2022). "The covariates adjusted for PFS were maximal tumor size, tumor number, and bilirubin and albumin concentrations, whereas the covariates adjusted for OS were maximal tumor size; tumor number; sex; bilirubin, albumin, and AFP concentrations; and portal hypertension." (PMID 35626044, 2022). "Serum levels of AST, ALT, GGT, total bilirubin, and hsCRP, PT, and INR showed significant increases, while platelet count and serum levels of albumin and Na showed significant decreases in patients with HCV-related liver disease compared with healthy controls (P < 0.05)." (PMID 36376416, 2022). "AUC, area under the curve; ALBI, albumin–bilirubin; MELD, model for end-stage liver disease." (PMID 35113969, 2022). "We did not include patients with infectious disease, liver disease, known coagulation disorder and heart disease when choosing our patient group since albumin also decreases independently of the tumor in case of liver failure and infection." (PMID 36496365, 2022). "Thus, we found an improvement at the end of follow-up in non-invasive markers of liver disease (liver stiffness, FIB-4, AST, ALT, and albumin) and a significant increase in CD4+ T-cells/mm3, improving the patient's health status." (PMID 33785040, 2021).